PTGS2 (prostaglandin-endoperoxide synthase 2)
Diseases named in the same sentence as PTGS2 in open-access papers (continued):
Sharing a sentence is not in itself a finding about the gene and the disease.
Oral Squamous Cell Carcinomas (2 papers, 2015 to 2024). "In oral squamous cell carcinoma (OSCC), PTGS2‐regulated VEGF signalling promotes the formation of new blood and lymphatic vessels, facilitating the spread of cancer to the regional lymph nodes." (PMID 38426619, 2024). "This study was designed to elucidate the expression pattern of PTGS2 and genes regulating VEGF signalling in patients with locally advanced oral squamous cell carcinoma." (PMID 38426619, 2024). "This study was designed to elucidate the expression pattern of PTGS2 and genes regulating VEGF signalling in patients with locally advanced oral squamous cell carcinoma (OSCC)." (PMID 38426619, 2024).
papilloma (2 papers, 2013 to 2020). A benign epithelial neoplasm that projects above the surrounding epithelial surface and consists of villous or arborescent outgrowths of fibrovascular stroma. "A similar behavior was observed in the case of the Inhba and Ptgs2 when their abundance was compared between papilloma and cSCCs." (PMID 23935450, 2013).
pyometra (2 papers, 2015 to 2021). "In the uterine tissue during canine pyometra, Prostaglandin-endoperoxide synthase 2 (PTGS2), a gene that is responsible for PG synthesis, is among the top genes for which expression is increased." (PMID 34404837, 2021). "Overexpression of PTGS2/COX2 was detected in pyometra, confirming previous report." (PMID 26222498, 2015).
rectal adenocarcinoma (2 papers, 2018 to 2022). "Furthermore, in the case of the top five downregulated DEGs in resistant CRC patients, a low expression level of PTGS2 was considered an unfavorable factor for both colon and rectum adenocarcinoma." (PMID 35885025, 2022).
respiratory infection (2 papers, 2020 to 2024). "There is no information surrounding a specific neonatal respiratory infection and the response of PTGS2 in the medulla at the neonatal age." (PMID 38879567, 2024). "There was a significant decrease in only two inflammatory mediators, PTGS2 and Stat6, in response to the respiratory infection, with no changes to any other mediator observed." (PMID 38879567, 2024).
SAPHO syndrome (2 papers, 2019 to 2025). SAPHO syndrome (acronym for Synovitis, Acne, Pustulosis, Hyperostosis and Osteitis) is an auto-inflammatory disease, mainly characterized by the association of neutrophilic cutaneous involvement and chronic osteomyelitis. "As PTGS2 inhibitors are considered to be a potential risk factor for bone healing, we suspect that the down-regulation of PTGS2 in SAPHO syndrome may contribute to the osteoarticular lesions in patients." (PMID 31395074, 2019).
sarcopenia (2 papers, 2022 to 2023). Progressive decline in muscle mass due to aging which results in decreased functional capacity of muscles. "The analyzed groups (geriatric control and patients with frailty syndrome and sarcopenia) all had significantly different mRNA levels of PTGS2 compared with healthy subjects at age 25–30 and above 50 years old." (PMID 37629065, 2023). "Muscle samples of elderly people with sarcopenia also showed alterations in ferroptosis-related factors, including prostaglandin-endoperoxide synthase 2 (PTGS2/COX2)." (PMID 37629065, 2023). "Geriatric control and patients with frailty syndrome and sarcopenia were characterized by a similar PTGS2 mRNA level." (PMID 37629065, 2023). "Another study found changes in ferroptosis related factors such as HO-1, SAT1 and prostaglandin-endoperoxide synthase 2 (Ptgs2) in muscle samples of elderly people with sarcopenia." (PMID 36406272, 2022). "Interestingly, in geriatric patients, a significant negative correlation was found between iron concentration and PTGS2 mRNA level (r = −0.47, p = 0.017); a similar but statistically not significant trend was also observed in the patients with sarcopenia." (PMID 37629065, 2023). "Despite the fact that the generalizability of the expression level of single genes with a complex functional test seems to be inadequate, the clinical picture presented thus far supports the idea that PTGES and PTGS2 may play a role in the pathology of sarcopenia." (PMID 37629065, 2023). "Nevertheless, in patients with sarcopenia, we noticed a significant negative correlation between the mRNA level of PTGES2 and PTGS2 and serum creatine kinase (CK) concertation." (PMID 37629065, 2023). "Additionally, in patients with sarcopenia, a negative correlation was also observed between creatine phosphokinase and the expressions of PTGES2 (COX2) and PTGS2." (PMID 37629065, 2023).
synovitis (2 papers, 2017 to 2021). Inflammation of a synovial membrane. "Expression levels of IL1B, IL6, CXCL8, TNF, PTGS2, and PTGER4 showed significant positive correlations with synovitis score." (PMID 33507995, 2021). "We found that expression levels of PTGS2 and PTGER4 were increased significantly with an increase in the synovitis score." (PMID 33507995, 2021). "With regard to comparison of the low-grade and high-grade groups with different grades of synovitis, expression levels of IL1B, CXCL8, TNF, and PTGS2 were significantly higher in the high-grade group than in the low-grade group." (PMID 33507995, 2021). "Expression levels of IL1B, IL6, CXCL8, TNF, PTGS2, and PTGER4 showed significant positive correlation with synovitis score." (PMID 33507995, 2021).
uveitis (2 papers, 2011 to 2025). An inflammatory process affecting a part of or the entire uvea. "Machine learning identified IFN-associated genes as robust predictors, while linear discriminant analysis pinpointed CCR2, CD180, GAPT, and PTGS2 as key risk factors in isolated uveitis and CA1, SIAH2, and PGS in systemic disease-associated uveitis." (PMID 40270958, 2025). "The genes that showed a significantly increased risk ratio for uveitis in the uveitis only group, and were upregulated in patients, included CCR2, CD180, GAPT, and PTGS2." (PMID 40270958, 2025).
ZIKV infection (2 papers, 2019 to 2022). "PTGS2 and TNF have both been implicated as being overexpressed during ZIKV infection, with TNF overexpression being directly associated with severe microcephaly." (PMID 35746681, 2022). "CXCL3, CXCL8, and PTGS2 were all slightly, but not significantly, induced following ZIKV infection, and the expression of all three inflammatory mediators was significantly decreased in the EGR1−/− infected cells as compared to the WT mock-infected cells." (PMID 35746681, 2022). "Thus, it would be interesting to further explore the role of EGR1 in regulating PTGS2 and TNF-α expression following ZIKV infection." (PMID 35746681, 2022).
acute lymphoblastic leukemia (1 paper, 2024). Leukemia with an acute onset, characterized by the presence of lymphoblasts in the bone marrow and the peripheral blood. "A recent study on Mexican adults with acute lymphoblastic leukemia showed that PTGS2 is highly downregulated compared to controls using transcriptomic microarray analysis." (PMID 39450252, 2024).
adenovirus infection (1 paper, 2023). "The expression levels of MMP1, IL6, IL8, and PTGS2 increased upon CH25H overexpression via adenovirus infection in human GFs." (PMID 38036731, 2023).
Airway obstruction (1 paper, 2026). Obstruction of conducting airways of the lung. "Among these, IL-1β can trigger PTGS2 to induce MUC5AC mucin expression through ERK or p38 MAPK, exacerbating airway obstruction, whereas TNF-α may induce PTGS2 to produce prostaglandin E2 (PGE2) and other substances, exacerbating airway inflammation." (PMID 41557720, 2026).
alcoholic liver diseases (1 paper, 2019). A disorder caused by damage to the liver parenchyma due to alcohol consumption. "As discussed in Section 3.2, “Target prediction of TCM,” ZZDHT decoction has been applied to treat alcoholic liver disease by targeting CYP2E1, XDH, NOS2, and PTGS2." (PMID 30846939, 2019). "The authors found that ZZDHT may exert antioxidant effects to regulate reactive oxygen species, thereby treating alcoholic liver disease by targeting cytochrome P450 2E1 (CYP2E1), xanthine dehydrogenase (XDH), nitric oxide synthase 2 (NOS2), and prostaglandin-endoperoxide synthase 2 (PTGS2)." (PMID 30846939, 2019).
alopecia (1 paper, 2022). Hair loss usually from the scalp. "K14-specific Ptgs2 overexpression mice showed elevated PGD2 levels in the skin and caused alopecia with impairment of hair follicles." (PMID 35162962, 2022).
asthenozoospermia (1 paper, 2025).
autoimmune thyroid disease (1 paper, 2025). Inflammatory disease of the thyroid gland due to autoimmune responses leading to lymphocytic infiltration of the gland. "For instance, IL1B was involved in mismatch repair, PTGS2 participated in the IL-17 signaling pathway and TNF signaling pathway, SELL was associated with autoimmune thyroid disease, and notably, all three genes were related to tyrosine metabolism." (PMID 40857330, 2025).
avascular necrosis (1 paper, 2022). Necrotic changes in the bone tissue due to interruption of blood supply. "This study detected five target genes (IL-1β, STAT3, CAT, PTGS2, and HMOX1) to further study the effects of quercetin, luteolin, kaempferol, cryptotanshinone, and naringenin on the expression of related genes in steroid-induced avascular necrosis of the femoral head." (PMID 35915795, 2022).
bacterial pneumonia (1 paper, 2023). Acute infection of the lung parenchyma caused by bacteria (e.g., Streptococcus pneumoniae, Haemophilus influenzae, Chlamydia pneumoniae, Mycoplasma pneumoniae, and Legionella pneumophila). "In cases of bacterial pneumonia, the mRNA expression of MAPK1 and CYP3A4 increased significantly, while those of PTGS1 and PTGS2 decreased synonym." (PMID 37741847, 2023).
biliary tract cancer (1 paper, 2012). "Data from our population-based study of biliary tract cancers in Shanghai suggested that variants in PTGS2, IL8, IL8RB, RNASEL, NOS2 and VEGF were associated with biliary tract cancer and/or stones." (PMID 23057767, 2012).
bronchiolitis (1 paper, 2022). Inflammation of the bronchioles characterized by swelling of the bronchioles and mucus accumulation. "We also observe an inverse correlation of both IL1R1 and PTGS2 with miR-146a-5p gene expression in bronchiolitis NPAs, suggesting that the reduction in this miRNA could be related to a failure of inflammation resolution." (PMID 36078154, 2022).
candida infection (1 paper, 2022). "In response to candida infection, PTGS2 activation promotes NF-kB and MAPK signaling pathways." (PMID 36482897, 2022).
cervical tumor (1 paper, 2023). "All these mediators were downregulated by piperine in cervical tumor cells, indicating the anti-inflammatory effect of piperine via PTGS2." (PMID 36678600, 2023).
choroidal melanoma (1 paper, 2021). Malignant tumor of melanocytes of the choroid. "Treatment of choroidal melanoma cell line (OCM1) cells with celecoxib (an inhibitor of PTGS2) effectively inhibits cell growth, proliferation, and promotes apoptosis." (PMID 34124047, 2021).
chronic hepatitis B (1 paper, 2021). "Patients with chronic hepatitis B had significantly higher PTGS2 expression compared with controls." (PMID 34301291, 2021).
Co-infection (1 paper, 2024). "Co-infection of monocytes with PRRSV-2 strain IAF-Klop and S. suis led to synergistic effects on the expressions of IL-6, CCL5, and TNF-α, and additive effects on productions of CCL4, CCL14, CCL20, IL-15, and PTGS2 (COX-2)." (PMID 38547254, 2024).
complex regional pain syndrome (1 paper, 2025). A chronic pain syndrome characterized by a disproportionate spontaneous or stimulus-induced pain, accompanied by a variably mixed myriad of autonomic and motor disorders including symptoms such as swelling, allodynia, skin blood supply and trophic disturbances. "PTGS2 is also implicated in complex regional pain syndrome (CRPS), where its expression correlates with inflammation-driven pain amplification." (PMID 40075716, 2025).
contact dermatitis (1 paper, 2021). An inflammatory skin condition caused by direct contact between the skin and either an irritating substance or an allergen. "Dermal fibroblasts were also found to secrete PGs in a PTGS2-dependent manner in both a three-dimensional fibroblast-containing collagen matrix and a murine model of irritant contact dermatitis." (PMID 34909715, 2021).
cyst (1 paper, 2023). A sac-like closed membranous structure that may be empty or contain fluid or amorphous material. "The higher abundance of PTGS2 mRNA and protein (p < 0.05) was indicated in IPC and IPC/SOC cyst, respectively, compared with all preovulatory follicles." (PMID 37173342, 2023).
demyelinating polyneuropathies (1 paper, 2012). "It has been shown that a significant up-regulation of PTGS2 was detected in sural nerves from patients with GBS and other demyelinating polyneuropathies." (PMID 22253732, 2012).
Dysarthria (1 paper, 2013). Dysarthric speech is a general description referring to a neurological speech disorder characterized by poor articulation. "The target of ‘Nabumetone’ is ‘Prostaglandin G/H synthase 2’ (PTGS2), the disease gene of ‘Sensory Ataxic Neuropathy, Dysarthria, And Ophthalmoparesis; Sando’ is ‘DNA polymerase subunit gamma-1’ (POLG)." (PMID 24244318, 2013).
eczema (1 paper, 2022). "Shikonin is the main chemical component of Comfrey; it can act on nine eczema-related targets, among which TNF and PTGS2 are the common targets of shikonin, gallic acid, and ellagic acid." (PMID 35907999, 2022).
erectile dysfunction (1 paper, 2019). Persistent or recurrent inability to achieve or to maintain an erection during sexual activity. "Schramek and Waldhauser showed that prostaglandin E1 injection was effective for erectile dysfunction; PTGS2 may have a role here." (PMID 31814838, 2019).
esophagitis (1 paper, 2010). An acute or chronic inflammatory disease affecting the esophageal wall. "Three SNPs in PTGS2 modulated esophagitis risk in our patient population: rs20417, rs5275, and rs689470." (PMID 20811626, 2010). "PTGS2:rs20417 was also associated with increased risk of esophagitis." (PMID 20811626, 2010).
Flavivirus Infections (1 paper, 2017). Infections with viruses of the genus FLAVIVIRUS, family FLAVIVIRIDAE. "Another gene linked to flavivirus infection that has a role in inflammation and pathological processes is the enzyme prostaglandin-endoperoxide synthase 2 (PTGS2), otherwise known as COX-2, which was significantly induced throughout the time-course of infection." (PMID 29036922, 2017).
fungal infection (1 paper, 2016). "This immune suppressive effect is in line with current results, demonstrating the positive impact on mRNA Ptgs2 expression and PGE2 secretion of the Gal-1 deficiency in macrophages from Lgals1−/− mice after fungal infection." (PMID 27698545, 2016).
H1N1 Influenza A (1 paper, 2025). "Network pharmacology indicates that CDC25B, PARP1, and PTGS2 are key target proteins involved in the interaction between S. ardesiacus isolates and H1N1 Influenza A." (PMID 40278270, 2025). "The degree, closeness, and betweenness values of 3.82, 7.54, and 23.17, respectively, indicated that three major proteins—CDC25B, PARP1, and PTGS2—are involved in the interaction between microbial isolates and H1N1 Influenza A." (PMID 40278270, 2025).
hemochromatosis (1 paper, 2023). A disorder of iron metabolism characterized by a triad of HEMOSIDEROSIS; LIVER CIRRHOSIS; and DIABETES MELLITUS. "Treatment with the potent but promiscuous TXNRD1 inhibitor, auranofin, in a hemochromatosis mouse model showed an increase in hepatic malondialdehyde (MDA), a product of lipid peroxidation, and Ptgs2 mRNA levels, which is highly associated with ferroptosis." (PMID 37087975, 2023).
HIV-associated dementia (1 paper, 2020). "In addition, IL-1β is a regulator of inflammatory reactions and is involved in the stimulation of the central nervous system through cyclooxygenase-2 (PTGS2/COX2), which is involved in neurodegenerative disorders such as MS, Down’s Syndrome, Alzheimer’s disease, and HIV-associated dementia." (PMID 32102262, 2020).
hyperandrogenism (1 paper, 2022). Excessive secretion of androgens from the adrenal glands or gonads. "PCOS is considered to be a chronic inflammatory disease, and multiple inflammation-related genes (such as interleukin-1 beta (IL1B), prostaglandin-endoperoxide synthase 2 (PTGS2)), as well as granule cells(GCs) in the inflammatory environment of PCOS patients, have been linked to hyperandrogenism." (PMID 35787810, 2022).
Hypoglycemia (1 paper, 2020). A decreased concentration of glucose in the blood. "In the oxidative stress marker panel, only PTGS2 differed between T2DM and controls (p < 0.0001), and comparison of baseline to hypoglycemia in T2DM subjects showed fibroblast growth factor 8 (FGF8) (p < 0.0001) was significantly different, after multiple testing correction." (PMID 32179763, 2020).
hypopharyngeal squamous cell carcinoma (1 paper, 2025). "CREB, ATF-2, and c-Jun stimulate transcriptional activation of the prostaglandin endoperoxide synthase-2 promoter via the CRE in nitric oxide-stimulated hypopharyngeal squamous cell carcinoma." (PMID 40871473, 2025).
irritable bowel syndrome (1 paper, 2023). Irritable bowel syndrome (IBS) is a chronic functional condition of the lower gastrointestinal (GI) tract characterized by abdominal pain or discomfort and disordered bowel habit (diarrhea, constipation, or fluctuation between the two). "Using a systems pharmacology approach and molecular docking, the researchers investigated potential pathways for BXD treatment in the fight against irritable bowel syndrome (IBS) and predicted promising drug targets, such as PTGS2, NOS2, and PRSS1." (PMID 37836654, 2023).
Lassa fever (1 paper, 2009). A viral hemorrhagic fever that is caused by the Lassa virus, which is transmitted by contact with infected rodents; it is characterized by fever, headache, malaise, myalgia, and hearing loss. "A dramatic and early drop in cyclo-oxygenase-2 gene (PTGS2) expression was observed in the primate model that could directly account for the drop in prostacyclin and platelet dysfunction described in Lassa fever." (PMID 19216742, 2009).
leptospirosis (1 paper, 2023). A contagious bacterial infection caused by spirochetes of the genus Leptospira. "Notably, prostaglandin E2 (PGE2), a product of the PTGS2 pathway, was found at higher levels in the sera of patients with acute leptospirosis and in the supernatant of MoDCs-P, possibly contributing to Treg induction, compared to those of healthy donors and MoDCs-NP, respectively." (PMID 37983293, 2023).
leukopenia (1 paper, 2024). "Herein, we found that poly I:C and LPS insults resulted in leukopenia and thrombocytopenia; an upregulation of 4HNE, MDA, and PTGS2 mRNA levels; lung tissue injury; and pro-inflammatory factor abnormalities." (PMID 38483700, 2024).
lung squamous cell carcinoma (1 paper, 2022).
Lymphatic Metastasis (1 paper, 2023). Transfer of a neoplasm from its primary site to lymph nodes or to distant parts of the body by way of the lymphatic system. "The expression of PTGS2 in the lymphatic metastasis group was significantly higher than that in the non-metastasis group (P<0.01)." (PMID 37274228, 2023).
lymphocytic tumor (1 paper, 2023). "Additionally, this approach allows us to identify the effects of chronic inflammation, represented by PTGS2 levels, on the acute or lymphocytic tumor infiltrate, which is represented by CTLA4." (PMID 38201508, 2023).